Y_RNA (Y RNA )
Gene: Miscellaneous RNA gene on chromosome 12 (32,705,403 to 32,705,506, reverse strand). Ensembl gene ENSG00000201563.
Homologues: Orthologues: chimpanzee Y_RNA (99% identical), macaque Y_RNA (97% identical). Paralogues in human: RNY1 (92% identical), Y_RNA (90% identical), Y_RNA (89% identical), RNY1P11 (88% identical), Y_RNA (88% identical), RNY1P13 (88% identical), RNY1P10 (87% identical), Y_RNA (87% identical), RNY1P12 (86% identical), RNY1P8 (86% identical), Y_RNA (86% identical), Y_RNA (85% identical), and 99 more.